ANGPTL4 (angiopoietin like 4)
Diseases named in the same sentence as ANGPTL4 in open-access papers (continued):
Sharing a sentence is not in itself a finding about the gene and the disease.
atherosclerosis (49 papers, 2017 to 2026). A disease characterized by the build-up of fatty material and calcium deposition in the arterial wall resulting in partial or complete occlusion of the arterial lumen. "In atherosclerosis, loss of function mutation of ANGPTL4 in humans was associated with an increased risk." (PMID 39311911, 2024). "Accumulating evidence indicates that ANGPTL4 is associated with TG metabolism and atherosclerosis progression." (PMID 35566578, 2022). "ANGPTL4 is a multi-functional protein implicated in different pathological disorders including cardio-pulmonary diseases, atherosclerosis, diabetes mellitus, malignancies, and nephritic syndrome." (PMID 36009579, 2022). "At the same time, accumulating evidence associated Angptl4 directly with the risk of atherosclerosis and T2D." (PMID 35321016, 2022). "A recent study in mice showed that the loss of ANGPTL4 in adipose tissue decreases circulating TG and cholesterol levels and atherosclerosis." (PMID 35566578, 2022). "ANGPTL4 influences a series of actions implicated in atherosclerosis (AS), including inflammation and lipid accumulation." (PMID 33750331, 2021). "Researchers have found that ANGPTL4 regulated circulating lipids, modulated angiogenesis, and associated diseases, and knockdown of ANGPTL4 reduces atherosclerosis in mice." (PMID 34041244, 2021). "Accumulating evidence associates the serum levels and gene polymorphisms of ANGPTL4 directly with the risk of atherosclerosis." (PMID 33750331, 2021). "Experiments on the regulation of Angptl4 expression within arterial macrophages have shown that formation of foam cells is suppressed by Angptl4 expression and leads to a lower risk of atherosclerosis." (PMID 31164103, 2019). "Genotypes of SNPs in 1654 individuals of Chinese Han population verified the potential function of the ANGPTL4 variants on circulating lipid levels and diseases that are related to atherosclerosis." (PMID 31164103, 2019). "We have previously demonstrated that germline deletion of ANGPTL4 results in reduced circulating TAGs and atherosclerosis while also causing severe inflammation and metabolic complications." (PMID 29563332, 2018). "Besides, hematopoietic cell-specific ANGPTL4 deficiency also increased both foam cell formation and atherosclerosis." (PMID 37634084, 2024). "Therefore, miR-134 potentially enhances plaque formation and atherosclerosis-associated inflammation through ANGPTL4." (PMID 39272765, 2024). "Angptl4 is already reported as a prognostic marker for ischemic stroke because higher levels of Angptl4 in the plasma were associated with poor prognosis in acute ischemic stroke patients and were a predictive biomarker in atherosclerosis." (PMID 37533068, 2023). "High ANGPTL4 is positively correlated with the risk of atherosclerosis and ischemic stroke." (PMID 36009579, 2022). "In addition, ANGPTL4 is known to regulate cellular energy homeostasis and ROS, and has been implicated in aspects of the pathogenesis of atherosclerosis, including endothelial dysfunction, oxidation of LDL, and reduced nitric oxide." (PMID 32796743, 2020). "Simultaneously, a Japanese study showed that circulating Angptl4 was significantly higher in patients with impaired glucose metabolism and that a deficiency in Angptl4 could improve lipid metabolism and protect against atherosclerosis." (PMID 31380419, 2019). "ANGPTL4 deficiency in adipocytes attenuates the progression of atherosclerosis." (PMID 29563332, 2018). "However, this is complicated by studies showing that loss of function of ANGPTL4 or treatment with a blocking antibody significantly lowers hypertriglyceridemia, a known risk factor for atherosclerosis, and studies have correlated ANGPTL4 levels with the risk of heart failure." (PMID 40723247, 2025).
atherosclerosis (continued). "SMC phenotypic switching is a key phenomenon underlying several vessel-narrowing diseases, such as atherosclerosis, and our study showed that ANGPTL4 could be a potential regulator of SMC differentiation by blocking the transition to macrophage-like cell types by downregulating KLF4." (PMID 36782020, 2023). "Because systemic ANGPTL4 injection may affect more than the inflammatory status, we further examined whether plaque stability, a key factor during the pathogenesis of atherosclerosis, may be causally involved in the alleviation of atherosclerosis." (PMID 36782020, 2023). "In atherosclerosis and ischemia, ANGPTL4 has been shown to play a protective role by promoting increased blood flow to the sites, stabilizing atherosclerotic plaques, and inhibiting inflammation." (PMID 40723247, 2025). "ANGPTL4 has been shown to play a role in the pathophysiology of several human diseases including atherosclerosis, various retinopathies, and several cancers." (PMID 40723247, 2025). "We demonstrate in this translational model that Angptl4 silencing potently attenuated hyperlipidemia and atherosclerosis development." (PMID 39259836, 2024). "Liver-targeted Angptl4 silencing potently attenuates hyperlipidemia and atherosclerosis development in APOE*3-Leiden.CETP mice, and liver-targeted ANGPTL4 silencing is well tolerated in non-human primates." (PMID 39259836, 2024). "In this mouse model of lipid-driven atherosclerosis development, the reduced atherosclerotic lesion formation was primarily a function of the reduced plasma lipid levels following Angptl3 and Angptl4 silencing." (PMID 39259836, 2024). "For example, genetic deletion of Angptl4 in adipose tissue safely attenuates hyperlipidemia and atherosclerosis development, but adipose-targeted drug delivery is currently not possible in humans." (PMID 39259836, 2024). "Among other anti-atherogenic effects such as reduction of cardiac and vascular inflammation, ANGPTL4 reduces the phenotypic transition of SMCs into macrophage-like cells in the ApoE−/− mouse model of atherosclerosis." (PMID 38952543, 2024). "This study suggests that ANGPTL4 promotes endothelial cell proliferation and inhibits PA-induced endothelial cell damage, thereby preventing the development of atherosclerosis." (PMID 38505420, 2024). "This study aims to compare the therapeutic potential of liver-specific Angptl3 and Angptl4 silencing to attenuate hyperlipidemia and atherosclerosis development in APOE*3-Leiden.CETP mice, a well-established humanized model for lipoprotein metabolism." (PMID 39259836, 2024). "Since short-term liver-targeted Angptl3 and Angptl4 silencing potently attenuated hyperlipidemia, we next assessed to what extent these treatments would also reduce atherosclerosis development over a treatment period of 12 weeks." (PMID 39259836, 2024). "Injection of ANGPTL4 into ApoE−/− mice fed with a high-fat diet suppressed the progression of atherosclerosis." (PMID 39272765, 2024). "To further develop clinical-translational approaches, we investigated the clinical characteristics of ANGPTL4 and validated the therapeutic efficacy of ANGPTL4 administration in an atherosclerosis mouse model." (PMID 36782020, 2023). "The anti-inflammatory effect of ANGPTL4 appears to be involved in suppressing the inflammatory responses of NOX-derived ROS that contribute to accelerated atherosclerosis." (PMID 36782020, 2023). "Researchers led by Youngkeun Ahn and Yong Sook Kim at Chonnam National University Hospital, Gwangju, South Korea, have shown that they can counter this process in a mouse model of atherosclerosis by treatment with a protein called ANGPTL4." (PMID 36782020, 2023).
atherosclerosis (continued). "ANGPTL4 was positively associated with cIMT in our work which is consistent with previous studies that showed a link between ANGPTL4 serum levels and atherosclerosis." (PMID 35488290, 2022). "Although ANGPTL4 is expressed in ECs and is induced by hypoxia, the EC-specific role of ANGPTL4 in TG partitioning and atherosclerosis has yet to be studied." (PMID 35289308, 2022). "Both Angptl4-ab and DLT treatment reversed the changes in lipid concentration, LPL activity, and atherosclerosis caused by CIH." (PMID 36285165, 2022). "Nevertheless, evidence indicates that ANGPTL4 does play a vital in atherosclerosis development, but the mechanism requires clarification." (PMID 35371605, 2022). "Nevertheless, ANGPTL4 has been also reported to have two-faced properties in relation to atherosclerosis." (PMID 36144281, 2022). "Together, these studies indicate that targeting ANGPTL4 in a tissue-specific manner can improve cardiometabolic health in rodent models of atherosclerosis and T2D." (PMID 35289308, 2022). "On the other hand, a protective effect of ANGPTL4 against inflammation and atherosclerosis has been reported." (PMID 35566578, 2022). "Since the circulating levels of Angptl4 have been reported to range from 455 to 961 ng/mL in patients with varying degrees of atherosclerosis." (PMID 35911520, 2022). "Angiopoietin-like 4 (ANGPTL4) is a protein secreted from adipose tissue and plays a critical role in the progression of atherosclerosis." (PMID 35566578, 2022). "ANGPTL4 influences the lipid metabolism thus involved in the pathogenesis of the chronic inflammatory process of atherosclerosis." (PMID 33750331, 2021). "In conclusion, this research depicted a pathogenic function of lncRNA H19 in promoting the development of atherosclerosis and revealed a new mechanism for ANGPTL4 modulation." (PMID 34820432, 2021). "We analyzed, therefore, changes in circulating ANGPTL3 and ANGPTL4 in obese patients with different metabolic phenotypes and their relation with impaired vasodilator reactivity, an early abnormality in atherosclerosis." (PMID 34440242, 2021). "lncRNA H19 promoted the expression of ANGPTL4 via competitively binding to miR-146a-5p, thus promoting lipid accumulation in atherosclerosis." (PMID 34820432, 2021). "Previous studies have demonstrated that the loss-of-function mutations in ANGPTL4 are associated with protection against coronary artery disease, indirectly hinting at a role of ANGPTL4 in atherosclerosis." (PMID 34440242, 2021). "Conversely, ANGPTL4-deficient mice exhibit increased plasma LPL activity, increased TG clearance, decreased plasma TG levels, and reduced atherosclerosis." (PMID 32849290, 2020). "The elevated expressions of ANGPTL4 and inflammatory cytokines suggest that the risk of ischemic stroke in haplogroup F may be partially due to its relatively enhanced inflammatory response during hypoxic-ischemic conditions, potentially facilitating the process of atherosclerosis." (PMID 32796743, 2020). "In contrast, hematopoietic cell–specific deletion of ANGPTL4 avoided these complications and resulted in increased atherosclerosis as a result of increased monocyte proliferation and enhanced lipid accumulation in macrophages and generation of foam cells." (PMID 29563332, 2018). "Together, these findings uncovered an essential role of AT ANGPTL4 in regulating peripheral lipid deposition, influencing whole-body lipid and glucose metabolism and the progression of atherosclerosis." (PMID 29563332, 2018). "Genetic knockout of ANGPTL4 protects APOE−/− mice against development of atherosclerosis and strongly suppresses the ability of the macrophages to become foam cells." (PMID 29940978, 2018). "We demonstrate that adipose ANGPTL4 governs plasma TAG levels by modulating LPL activity, and as a consequence, impacts associated metabolic outcomes including progression of atherosclerosis and glucose homeostasis in mice." (PMID 29563332, 2018).
atherosclerosis (continued). "In accordance, several reports have also revealed the impact of ANGPTL4 variations on the development of atherosclerosis." (PMID 30323852, 2018). "In summary, we determined the role of adipose ANGPTL4 in regulating lipid and glucose metabolism and vascular inflammation and elucidate its importance in adiposity and development of atherosclerosis." (PMID 29563332, 2018). "It is also notable that in a recent study, inactivation of the angiopoietin-like protein 4 gene (ANGPTL4) was found to result in decreased cardiovascular and atherosclerosis diseases risk, specifically coronary artery disease and ischemic stroke." (PMID 30400262, 2018). "Additionally, they found that ANGPTL4 levels were downregulated in atherosclerosis mouse serum and were closely related to autophagy-related proteins in atherosclerosis mouse aortic tissue." (PMID 38505420, 2024). "However, a global Angptl4 knockout in mice found protective effects, while a hematopoietic cell-specific knockout showed detrimental effects on atherosclerosis." (PMID 39311911, 2024). "In this study, where the degree of Angptl4 silencing was larger than that of Angptl3, Angptl4 silencing consequently induced a greater attenuation of atherosclerosis development than Angptl3 silencing, while the effects of Angptl4 and combined Angptl3/4 silencing were comparable." (PMID 39259836, 2024). "Our data point towards several potential mechanisms through which hepatic Angptl4 silencing may attenuate hyperlipidaemia, and accordingly atherosclerosis development, which only partly overlap with those of Angptl3 silencing." (PMID 39259836, 2024). "Given the fundamental contribution of inflammation to atherosclerosis, we assessed the role of ANGPTL4 in the development of atherosclerosis and determined whether ANGPTL4 regulates atherosclerotic plaque stability." (PMID 36782020, 2023). "Since the serum levels of ANGPTL4 are related to cIMT, this molecule may represent a biomarker of subclinical atherosclerosis in these patients." (PMID 35488290, 2022). "Therefore, it is reasonable to believe that ANGPTL4 plays an important role in the occurrence and development of human atherosclerosis." (PMID 33750331, 2021). "Thus, our research offers novel acumens into the molecular role of lncRNA H19/miR-146a-5p/ANGPTL4 signaling pathway in lipid accumulation and highlights lncRNA H19 as a promising therapeutic target for atherosclerosis." (PMID 34820432, 2021). "The role of ANGPTL4 in atherosclerosis development is unclear." (PMID 34742313, 2021). "In this regard, the results of the current study may provide a potential link between ANGPTL4 and atherosclerosis, given that a defect in the endothelium-dependent vasodilator function is considered the earliest stage in the atherogenic process." (PMID 34440242, 2021). "ANGPTL3 may promote the development of atherosclerosis and ANGPTL4 may protect against atherosclerosis." (PMID 34742313, 2021). "ROC curve analyses indicated that ANGPTL3 concentrations above 30.5 ng/mL can predict atherosclerosis with a sensitivity of 71.2% and specificity of 75.3%, and that ANGPTL4 levels below 497.5 ng/mL can predict atherosclerosis with a sensitivity of 63.9% and specificity of 74.5%." (PMID 34742313, 2021). "Furthermore, lncRNA H19 served as a microRNA (miRNA) sponge in the positive regulation of the ANGPTL4 expression by sponging miR-146a-5p, thereby promoting lipid accumulation in atherosclerosis." (PMID 34820432, 2021). "Thus, it is critical to comprehend the molecular mechanisms involved in ANGPTL4 regulation for the development of new therapeutic interventions for atherosclerosis." (PMID 34820432, 2021). "Therefore, the prevention of ANGPTL4-mediated lipid accumulation is an important mechanism by which lncRNA H19 facilitates lipid accumulation and aggravates atherosclerosis." (PMID 34820432, 2021).
atherosclerosis (continued). "All these results suggested that ANGPTL3 and ANGPTL4 were better risk predictors of atherosclerosis independent of lipids, smoking, and other CHD risk factors that we studied." (PMID 34742313, 2021). "Although ANGPTL4 inhibition is effective in lowering TGs in mice and primates and also reduces atherosclerosis progression, an important question remains regarding the safety of this approach due to the mesenteric lymphadenopathy seen in high fat-fed animals in which ANGPTL4 is blocked." (PMID 32849290, 2020). "Thus, while it was beyond the scope of our current study to test this additional blood marker, future studies should test serum ANGPTL4 activity to assess the mechanism of triglycerides as a marker of atherosclerosis." (PMID 30400262, 2018). "Several studies have attempted to address the impact of ANGPTL4 on atherosclerosis development." (PMID 30323852, 2018). "ANGPTL4 suppresses foam cell formation to reduce atherosclerosis development." (PMID 30323852, 2018). "Importantly, we described how AT ANGPTL4 modulation of lipid metabolism results in improved glucose tolerance, insulin sensitivity, and protection against the progression of atherosclerosis." (PMID 29563332, 2018). "Whether and how ANGPTL4 binds to the cell surface receptors in ECs to regulate the expression of cell adhesion molecules and contribute to atherosclerosis requires further investigation." (PMID 29563332, 2018). "Five of them (ANGPTL4, APOB, BRAP, LPA, and ZPR1), were associated with increased levels of arteriosclerosis/atherosclerosis and risk of CVD, whereas four (DUSP13, FN1, IL6R, and MMP12) were associated with reduced levels of arteriosclerosis/atherosclerosis and risk of CVD." (PMID 42133815, 2026). "ANGPTL4 has been shown to be involved in many biological processes, including glucose and lipid metabolism, angiogenesis, and wound healing, with implications in diseases such as type 2 diabetes, cardiovascular (e.g., atherosclerosis) and renal diseases, and cancer." (PMID 40723247, 2025). "Furthermore, the KLF4 reduction promoted by angiopoietin-like 4 (ANGPTL4)-transforming necrosis factor alpha (TNFα)-NADPH oxidase 1 (NOX1) axis plays a role in the protective effect of the anti-inflammatory ANGPTL4 protein in atherosclerosis." (PMID 38952543, 2024). "The loss of ANGPTL4 in these tissues increases LPL activity and accelerates the catabolism of triglyceride-rich lipoproteins, reducing circulating triglycerides and low-density lipoprotein–cholesterol (LDL-C), which protects against the progression of atherosclerosis." (PMID 39728292, 2024). "Our results reveal that ANGPTL4 treatment inhibits atherogenesis and suggest that targeting vascular stability and inflammation may serve as a novel therapeutic strategy to prevent and treat atherosclerosis." (PMID 36782020, 2023). "Similarly, ANGPTL4 reduces the inflammatory responses and decreases the number of immune cells (monocytes and macrophages) accumulating in the atherosclerotic plaque in ANGPTL4 TG E3L mice, indicating the upregulation of ANGPTL4 expression can prevent or slow the progression of atherosclerosis." (PMID 35371605, 2022). "However, the specific role of ANGPTL4 in atherosclerosis progression is controversial." (PMID 35371605, 2022). "The findings from this study suggest that interventions capable of decreasing ANGPTL4 expression, specifically in AT, may improve glucose homeostasis and lessen atherosclerosis burden while avoiding the deleterious systemic effects observed with interventions that knock down ANGPTL4 globally." (PMID 29563332, 2018). "Loss of function mutations in ANGPTL4 and genetic variations in PLTP that attenuate its plasma activity have been associated with an attenuated risk of coronary artery disease, emphasizing the relevance of ANGTP4- and PLTP-mediated processes on the development of atherosclerosis." (PMID 29587751, 2018).